LDHA (lactate dehydrogenase A)
Diseases named in the same sentence as LDHA in open-access papers (continued):
Sharing a sentence is not in itself a finding about the gene and the disease.
tumor (continued). "LDHA promotes malignant progression of tumours by increasing the production of lactic acid, accelerating glycolysis, regulating the production of reactive oxygen species, and regulating many cancer-related proteins." (PMID 38288377, 2024). "IHC results also demonstrated that tumors with sh-LDHA had abundant immune cell infiltration and slower tumor proliferation." (PMID 38664705, 2024). "Tumor cells, through the overexpression of lactate dehydrogenase A (LDHA) among other mechanisms, lead to excessive lactate production." (PMID 39654883, 2024). "The lactate dehydrogenase isoenzymes (LDH) are tetramers composed of LDHA and LDHB, and their aberrant expression is often associated with cellular metabolism and tumor progression." (PMID 38511143, 2024). "Similar findings were observed in LDHA inhibition groups: Pan Kla and H3K18la levels were suppressed compared to the control tumor tissues." (PMID 38711083, 2024). "An association of an impaired LDH activity and a reduced stress response has been confirmed in tumor cells with a genetic knockout of LDHA and LDHB." (PMID 38229111, 2024). "The results showed that GPX3 and DOCK4 expression was significantly upregulated in normal cell lines, while LDHA expression was significantly upregulated in tumor cell lines." (PMID 38213730, 2024). "Similar to the mechanism of elevated lactate in solid tumor environment, tumor cells of hematologic malignancies take up a large amount of glucose and produce lactate via lactate dehydrogenase A (LDHA) due to genetic changes and tumor hypoxia." (PMID 38396050, 2024). "In this study, we elucidate the connection between FASN and LDHA, pivotal metabolic genes, and their correlation with tumor grade and therapy response using datasets from public repositories." (PMID 39044184, 2024). "In this study, we elucidate that ZBTB7B, a member of the ZBTB family, functions as a transcriptional regulator of LDHA, the key rate-limiting enzyme controlling lactate production in tumor cells." (PMID 39107297, 2024). "LDHA has diversified biological roles in cancer progression, such as inducing proliferation, promoting invasion, resulting in tumor metastasis, etc.." (PMID 38709280, 2024). "The promoter methylation level of LDHA was significantly lower in 13 tumor groups than in the normal group." (PMID 38291366, 2024). "The results showed that SLC2A1-DT knockdown obviously inhibited HCC tumor growth, HK2 and LDHA expression, tumor weight, and lung metastasis in nude mice, which was remarkably abolished by β-catenin overexpression." (PMID 38481809, 2024). "We demonstrate that pharmacologically targeting LDHA redirects intratumoral glucose utilization from tumor cells to T cells, favoring antitumor immunity." (PMID 39225102, 2024). "that LDHA plays an active role in antiviral and anti-tumor activities by promoting NK cell activation receptor signaling and effector functions." (PMID 39286242, 2024). "According to current study, we reveled that LDHA expression were dramatically upregulated in 14 tumor tissues compared to normal tissues." (PMID 38709280, 2024). "Conversely, knockdown of either PGC-1β or LDHA suppressed glycolysis, increased reactive oxygen species (ROS) formation and apoptosis, suppressed tumor growth and enhanced mouse survival." (PMID 37361580, 2023). "In present work, LDHA degradation was proven to be of considerable significance for ferroptosis and tumor progression." (PMID 36923931, 2023). "For example, lactic acid (highly expressed in tumor tissue) was downregulated in the tumors of mice treated with Akkermansia, with confirmed downregulation of lactate dehydrogenase-A enzyme via immunofluorescence." (PMID 38055306, 2023). "For example, FX-11 is a selective inhibitor of LDHA that shows antitumor activity in a mouse transplantation tumor model and is a potential target for cancer therapy." (PMID 37965331, 2023).
tumor (continued). "Overexpression of PGC-1β or LDHA potentiated glycolysis metabolism and increased cell proliferation and tumor growth." (PMID 37361580, 2023). "As the upstream regulators of LDHA, miR-383 and miR-142-3p exerted anti-tumor effects via negatively regulating LDHA expression." (PMID 37649103, 2023). "Inter-tumor Core and Rim regions showed significantly higher relative expression of hypoxia response genes, including LDHA, VEGFA, LOX, PLAUR, SERPINE1, and IGFBP3." (PMID 37434262, 2023). "Lactate metabolism was active in tumor cells and vSMCs, and LDHA, MCT1, and MCT4 were substantially expressed in tumor cells, according to single-cell analysis." (PMID 37795453, 2023). "IGFBP1 promotes RCC tumor energy metabolism, including glucose uptake, lactate survival, and extracellular acidification rate, by recognizing the m6A modification site on LDHA mRNA and enhancing its mRNA stability, thereby accelerating tumor energy metabolism." (PMID 38117350, 2023). "Targeting lactate dehydrogenase-A (LDH-A) in tumor cells can reduce the level of oxidative phosphorylation in tumors and enhance the efficacy of anti-hPSMA CAR-T cells treatment." (PMID 37342333, 2023). "LDHA, which catalyzes pyruvate into lactate, is a central player in glycolysis, and it has been reported that LDHA is involved in tumor progression through lactate production in many types of cancer." (PMID 37733442, 2023). "Mechanistically, IGF2BP1 recognized the m6A modified sites on LDHA mRNA and enhanced its mRNA stability, thereby accelerating tumor energy metabolism." (PMID 36691477, 2023). "High expression of LDHA is correlated with tumour progression in several cancer types, like renal cancer, pancreatic cancer, breast cancer, or GC." (PMID 38213532, 2023). "Certain LDHA inhibitors at the molecular level have notable impacts on tumor load, metastasis, and cellular demise." (PMID 37965333, 2023). "Consistent with the importance of glycolysis for NK cell tumor control, deleting LDHA in NK cells also impaired tumor clearance through impaired IFN-γ production and cytotoxic capacity." (PMID 36710923, 2023). "Reducing LDHA expression significantly increased the sensitivity of cancer cells to gemcitabine and inhibited tumor progression." (PMID 37391503, 2023). "Our study also showed that pharmacological LDHA inhibition by FX11 successfully reduced tumor volumes and increased both the intratumoral infiltration and cytotoxic activity of CD8+ T cells in CAF-rich PDAC tumors." (PMID 37733442, 2023). "We initially used single-cell sequencing data to determine the expression levels of GLUT3 and lactate dehydrogenase A (LDHA) in primary tumor, tumor-adjacent normal, and metastasis tumor tissues." (PMID 38041125, 2023). "Studies have shown that compared with the chemoradiotherapy-sensitive group, the expression of LDHA in tumor tissues of the chemoradiotherapy-resistant group is upregulated, and LDHA is also relatively highly expressed in CC cells." (PMID 37692844, 2023). "High expression of both PKM2 and LDHA has previously been shown in cancer cells, and promotes tumor progression." (PMID 37553596, 2023). "LDH possesses five isozymes where the fifth form or LDH-5, also known as LDHA is upregulated in most of the tumor cells, thus inhibiting LDHA decreases tumor development and invasiveness." (PMID 36583135, 2023). "And the results denoted that PC tissues showed higher FOXQ1 and LDHA protein levels than that in the nearby non-tumor tissues." (PMID 37875474, 2023). "Along this line, reducing lactate level in the TME by deleting lactate dehydrogenase A (LDHA) or through the administration of 2-deoxyglycose potentiates anti-tumor immunity by decreasing M2-like macrophage polarization." (PMID 37740232, 2023). "Reducing tumor glycolysis by suppressing lactate dehydrogenase A (LDH-A) and the concomitant acidification of the TME have been shown to increase T and NK cell abundance and activity while reducing the number of MDSC." (PMID 37760634, 2023).
tumor (continued). "In this study, the similar phenomenon was also found, phosphorylation of Y239 in LDHA was observed to diminish for 2.2-fold and 1.4-fold with the phenotype of tumor inhibition in PZH and sora groups compared to control sample." (PMID 36732657, 2023). "As mentioned in the previous section, studies have shown that lactate can promote tumor progression by regulating MOESIN lactylation in Tregs cells, and inhibition of LDHA can significantly reduce lactylation level and tumor load." (PMID 37965331, 2023). "Specifically, release of D2HG by tumor cells can induce aerobic glycolysis in peritumoral neurons signified by LDHA upregulation through an mTOR mediated mechanism, which in turn leads to neuronal hyperactivity and promotes seizures." (PMID 38026690, 2023). "At present, the application of LDHA in tumor tissues has been confirmed by some studies, and its reduction in vivo can delay tumorigenesis." (PMID 38264652, 2023). "These activities enhanced aerobic glycolysis and LDHA expression, which promoted PC cell proliferation, tumor stemness, invasion, and metastasis." (PMID 37875474, 2023). "Under hypoxic environments, HIF-1α promotes the migration of CD8+ T cells into tumor tissues, and its activation leads to an increase in lactate dehydrogenase A, which converts α-KG to L-2-HG." (PMID 37563735, 2023). "The use of a lactate dehydrogenase A (LDHA) blockade inhibited tumor growth and MDSCs activation as well as antitumor immunity after RT." (PMID 36765726, 2023). "Apigenin has been demonstrated to decrease GLUT1, HK2, PKM2, and LDHA production in tumor cells, and galangin has been shown to bind to the PKM2 site." (PMID 37892405, 2023). "LDHA phosphorylation provides invasive signals in metastatic cancer cells by regulating redox status, and LDHA can also enhance tumor progression by possessing molecules related to EMT." (PMID 37853445, 2023). "These genes include VEGF, erythropoietin, lactate dehydrogenase A and glucose transporters, which orchestrate angiogenesis, erythropoiesis, anaerobic metabolism, tumor immune evasion, and other events in the tumor region." (PMID 36998063, 2023). "Especially in PCa, high LDHA expression in PC-3 cells induces a favorable tumor microenvironment for tumor progression." (PMID 35278714, 2023). "Tumour cells with IDH mutation will express less MCT1/4, LDHA also decreases, and, thus, the production of lactic acid is reduced." (PMID 37108242, 2023). "This study shows that circRARS can promote glycolysis and tumor progression in NSCLC by regulating LDHA." (PMID 36628612, 2023). "LDHA is overexpressed in many types of cancer and plays a crucial role in tumor proliferation, invasion, and metastasis." (PMID 37443682, 2023). "Phosphorylation at tyrosine 10 by upstream kinases, HER2 and SRC has been reported to induce activation of LDHA promoting cancer cell invasion, anoikis resistance, and tumor metastasis." (PMID 37507768, 2023). "Thirty-nine of fifty-five GBM samples (70.91%) were LDHA-positive, and all harbored LDHA-nuclear translocation tumor cells." (PMID 37298317, 2023). "GLUT3 and LDHA expression levels showed an increasing trend in the tumor-adjacent normal, primary tumor, and metastasis tumor groups." (PMID 38041125, 2023). "LDHA is highly expressed in colorectal and other malignant tumors and is closely related to tumor proliferation and metastasis." (PMID 37693915, 2023). "In ccRCC, overexpression of PCK1 can suppress tumor progression via inhibition of lactate dehydrogenase A (LDHA), and patients with high PCK1 expression had better prognosis." (PMID 37062825, 2023). "In HCC, LDHA silencing has been demonstrated to impede tumor development and promote CD4+ T-cell infiltration." (PMID 37287752, 2023).
tumor (continued). "In summary, we have demonstrated that inhibition of the key gene LDHA in the tumor glycolytic metabolism significantly improves the immune microenvironment and delays tumor burden increase in the context of ABHD17C overexpression." (PMID 37273016, 2023). "We found the expression of LDHA and LAMP2 was highly elevated in the tumor regions and positively associated with a poor clinical stage of CRC." (PMID 38136340, 2023). "Stabilisation of LDHA resulted in enhanced glycolysis and promoted tumour cell progression, metastasis, and growth." (PMID 38213532, 2023). "First, for liver tissues in the Human Protein Atlas, despite high LDHA staining in both the cytosol and the nucleus, some tumor tissues exhibited higher nuclear staining than normal tissues, especially with the antibody CAB069404." (PMID 37779146, 2023). "In conclusion, ROS accumulation in IDH wild-type GBM tumor cells leads to the entry of LDHA to the nucleus and promotes the metabolism of BCAAs." (PMID 37298317, 2023). "It has been identified that LDHA was overexpressed in various cancers and involved in tumorigenesis and tumor growth." (PMID 37925501, 2023). "Alternatively, Apolipoprotein L3 enhances colorectal cancer CD8+ T cell anti-tumor immunity by promoting LDHA-mediated ferroptosis." (PMID 38264652, 2023). "The mutation mediated by VHL/HIF-1α can up-regulate the expression of glucose transporter 1 (GLUT-1) in ccRCC, and the glycolysis related gene lactate dehydrogenase A (LDHA) also strongly expresses in several tumor cell lines and RCC." (PMID 36969848, 2023). "According to a recent study, phosphorylation and activation of LDHA can promote tumor invasion and metastasis." (PMID 37427142, 2023). "For example, our study has reported that lactate dehydrogenase A (LDHA)-catalyzed lactate induces tumor acidic microenvironment to strengthen the binding capacity between USP28 and MYC, leading to MYC-driven breast cancer stem-like traits." (PMID 37845207, 2023). "Our study provides insight regarding the crosstalk among tumor cells, CAFs, and immune cells mediated by lactate and offers therapeutic strategies for targeting LDHA enzymatic activity in PDAC cells." (PMID 37733442, 2023). "A number of previous studies have shown a correlation between LDHA activity and tumor growth and metastasis." (PMID 35278714, 2023). "By contrast, tumor cells anaerobically convert pyruvate into lactate via LDHA in a phenomenon termed the Warburg effect." (PMID 37461556, 2023). "For example, LDHA is highly expressed in various cancers, and its knockdown notably inhibits tumor growth." (PMID 37398932, 2023). "Mechanistically, we uncovered SPRY2 interfered with SRC-LDHA interaction to inhibit LDHA phosphorylation and suppress glycolysis in tumor stroma." (PMID 37507768, 2023). "LDHA is a critical regulator in tumor aerobic glycolysis, and critical literature reveals its critical function in tumorigenesis." (PMID 36691477, 2023). "Inhibition of LDHA gene expression suppresses tumor growth and impairs vascularization, indicating a functional role of LDHA in aberrant NV." (PMID 36674619, 2023). "Since LDHA is a key player in the conversion of pyruvate to lactate and in the maintenance of glycolysis, targeting LDHA was shown to reduce tumor growth by suppressing glycolysis." (PMID 37110218, 2023). "SORD has been observed to suppress tumor growth and stemness via regulation of lactate dehydrogenase A (LDHA) expression and mitochondrial dynamics, which in turn enhances necroptosis." (PMID 37436087, 2023). "Taken together, these results further suggested the molecular mechanism by which APOL3 controls tumor proliferation, ferroptosis and anti-tumor immunity via promoting ubiquitylation-related degradation of LDHA in CRC." (PMID 36923931, 2023).
tumor (continued). "LDHA over-expression and subsequent lactate production are thought to promote tumor growth and metastasis by multiple mechanisms, including protection from reactive oxygen species, enhanced biomass synthesis, and increased cell motility." (PMID 37107600, 2023). "Conversely, an LDHA-inducible knock-out significantly inhibited TRAMP tumor growth and the formation of lymph node and visceral metastasis, highlighting the need for LDHA activity and lactate synthesis in TRAMP tumor progression." (PMID 37444583, 2023). "IHC analysis revealed that LDHA and LDHB expression profiles were significantly associated with tumor grade, stage, size, and overall survival (OS)." (PMID 37547725, 2023). "Key enzymes involved in this process, such as PGC1α, PKM2, ALDOA, and LDHA, can directly influence tumor progression and metastasis." (PMID 37197432, 2023). "We identified lactate metabolism markers for ccRCC cell types and found high expression levels of LDHA in tumor cells and CD8+ T cells." (PMID 37795453, 2023). "Using RT‐PCR, we observed that AZD‐6482 significantly inhibited expression of three tumor survival markers, LDHA, PPAT, and SMS (t‐test, p < 0.05)." (PMID 35676822, 2023). "LDHA overexpression favors pyruvate to lactate conversion, leading to tumor microenvironment acidification and aiding cancer progression and metastasis." (PMID 37915411, 2023). "As a crucial carcinogen, LDHA is particularly closely related to angiogenesis, tumor growth, and epithelial–mesenchymal transition in various tumors, containing OSCC." (PMID 37398901, 2023). "In contrast, another study showed that LDHA is crucial for the anti-tumor and anti-viral functions of murine NK cells." (PMID 36330529, 2022). "At the same time, the inhibition of LDHA suppresses tumor formation and progression, indicating an important role for LDHA in the malignant transformation process." (PMID 36230479, 2022). "The knockdown of lactate dehydrogenase A (LDHA) in tumor cells by RNAi nanoparticles, pyruvate metabolism, is reprogrammed to increase CD8+ T and NK cells infiltration." (PMID 35992338, 2022). "Western blot showed that a decrease in the expression levels of PKM2, GLUT-1, HK1, HK2, PKM1, and LDHA decreased in tumor cells and an inhibition of glycolysis and cell proliferation." (PMID 36284386, 2022). "The regulation of tumor pH levels by pharmacological inhibition of pH-responsible proteins (monocarboxylate transporters, H+-ATPase, etc.)and lactate dehydrogenase A is also a promising anticancer strategy." (PMID 36106097, 2022). "Invasive tumor spheroids from P3 stem‐like cells were included in paraffin and LDHA and LDHB expressions were analyzed in coronal sections." (PMID 36278433, 2022). "Inhibition or a decrease in expression of MCT1, MCT4 and LDHA in cancer cells slowed down tumor growth." (PMID 36582801, 2022). "XIST knockdown inhibited ARF6, N-cad, GLUT1, and LDHA protein expression and increased E-cad protein expression in tumor tissues." (PMID 35899235, 2022). "Only a few cells were found positive for LDHA in peripheral and invasive regions of the tumor, such as in the corpus callosum." (PMID 36278433, 2022). "LDHA is also an important protein in glycolysis, and this process drives tumor progression through a c-Myc-LDHA axis whose levels can be additionally modulated by the Wnt/β-catenin signaling." (PMID 35500936, 2022). "As the targeted gene of PKM2, LDHA catalyzes pyruvic acid to lactic acid and generates excessive lactic acid via hyperactivation in tumor cells." (PMID 35013150, 2022). "Overall, the pyruvate to lactate ratio is dependent on multiple factors including the monocarboxylate transporters MCT1, MCT4 but also LDHA expression and activity, depending on the tumor models." (PMID 35327519, 2022). "LDHA inhibitors are therapeutically a major target to inhibit tumor growth as known in lung cancer and a xenograft transplanted tumor, although LDHB is also a target." (PMID 36077431, 2022).